ADAM9 (ADAM metallopeptidase domain 9)
Diseases named in the same sentence as ADAM9 in open-access papers (continued):
Sharing a sentence is not in itself a finding about the gene and the disease.
melanoma (continued). "Up to date, only ADAM9, MMP7 and PIK3R2 have been validated as direct miR-126-3p&5p target genes in drug treatment-naïve melanoma cells." (PMID 31227006, 2019). "The cordycepin treatment downregulated the expression of ZEB1, HMGA2 and TWIST1 by more than 50% but had minimal effects on ADAM9, RAC1, SALL4, CTNNB1, ZEB2 and YES1 in these two melanoma cell lines." (PMID 25868853, 2015). "The overexpression of miR-126-3p/5p was shown to significantly induce apoptosis, and activate caspase-3 and caspase-7 by directly regulating ADAM9 and MMP7 in melanoma." (PMID 25759982, 2015). "Among them, only four miR-126&126* putative targets were shared by both melanomas being two of them, the solute carrier family 7, member 5 (SLC7A5) and ADAM9 (and this paper) already confirmed as direct targets of miR-126." (PMID 23437250, 2013). "Among a number of options, we focused on ADAM9, MMP7 and osteopontin (OPN) for their important role in melanoma progression." (PMID 23437250, 2013). "Looking for the effectors of these antineoplastic functions, we identified ADAM9 and MMP7, two metalloproteases playing a pivotal role in melanoma progression, as direct targets of miR-126&126*." (PMID 23437250, 2013). "The related metalloproteases ADAM9 (GeneID: 8754) and ADAMTS13 are upregulated in primary melanoma tumors and in melanoma cell lines, respectively." (PMID 18454205, 2008). "Therefore, ADAM-9-mediated proteolytic activities of melanoma cells and stromal fibroblasts also contribute to ECM remodelling to produce a TME suitable for melanoma cell migration and invasion." (PMID 34067929, 2021). "As this increase was detected in fibroblasts monocultures, it indicates that enhanced matrix secretion results from the ablation of ADAM9 rather than cross-communication between melanoma cells and fibroblasts." (PMID 32906814, 2020). "In summary, we have shown that the expression of ECM components during melanoma development is altered in the absence of ADAM9." (PMID 32906814, 2020). "We have recently shown that grafted melanoma cells in the skin of mice lacking ADAM9 generated larger tumors because of increased growth of melanoma cells in vivo and confirmed by increased proliferation of melanoma cells in vitro." (PMID 32906814, 2020). "To investigate the actual contribution of ADAM9 and MMP7 modulation to miR-126&126*-dependent outcomes, we tested the effects deriving from separately knocking-down these two genes in A375M and Me665/1 melanoma cells." (PMID 23437250, 2013). "In melanoma cells the low or absent levels of miR-126&126*, unblocking ADAM9 and MMP7, should result in an increased activation of pro-HB-EGF, consequently producing a higher quantity of HB-EGF-C translocation into the nucleus." (PMID 23437250, 2013). "In addition, as ADAM9 and MMP7 share a role in the proteolytic cleavage of the HB-EGF precursor, we looked for the effectiveness of this regulatory pathway in melanoma, confirming the decrease of HB-EGF activation as a consequence of miR-126&126*-dependent downmodulation of ADAM9 and MMP7." (PMID 23437250, 2013). "Besides, it may play a tumor suppressor role by directly regulating ADAM9 and MMP7 in melanoma." (PMID 33880366, 2021). "Hence, we provide evidence that ADAM9 can release a fragment of collagen type I, but not degrade it, and that indirectly, ADAM9 contributes to the regulation of collagen type I expression in peritumoral areas, thereby providing modulation of B16F1 cell proliferation during melanoma development." (PMID 32906814, 2020). "Moreover, treatment of primary or metastatic melanoma cells with anti-miR-126 and/or 126* LNA oligonucleotides for 48 hours showed a significant increase in the levels of ADAM9 and MMP7 compared with negative control-treated cells as judged by western blot analysis." (PMID 23437250, 2013).
glioma (20 papers, 2016 to 2025). A benign or malignant brain and spinal cord tumor that arises from glial cells (astrocytes, oligodendrocytes, ependymal cells). "Taken together, these results reveal reversed expression patterns between miR-1272 and ADAM9 and indicate that the expression of ADAM9 is associated with the severity of glioma." (PMID 33260155, 2020). "As a direct target of miR-1272, ADAM9 plays an important role in the progression of various glioma cell lines, supporting other studies that have reported that ADAM9 acts as an oncogene and is associated with tumor progression and poorer clinical outcomes." (PMID 33260155, 2020). "Our study demonstrated that ADAM9 mRNA expression was associated with tumor grade and histological type in gliomas." (PMID 27571068, 2016). "We observed a significant association between ADAM9 expression and histological type in patients with lower-grade gliomas (p < 0.001, Chi-square test)." (PMID 27571068, 2016). "ADAM9 mRNA expression was observed to be associated with tumor grade and histological type in glioma patients." (PMID 27571068, 2016). "Additionally, overexpression of ADAM9 inhibited the migration and invasion of glioma cells caused by USP39 depletion in vitro." (PMID 33811456, 2022). "It was reported that the mRNA levels of ADAM9 were positively associated with histological type and tumor grade in human glioma and could act as a prognostic factor in patients with lower‐grade glioma." (PMID 33811456, 2022). "In addition, ADAM8 and ADAM19 are correlated with the invasive activity of glioma cells and unfavorable survival, while ADAM9, -10 and -17 are associated with tumor grade and histological type of gliomas and can be used as prognostic factors." (PMID 34638718, 2021). "The authors concluded that ADAM9 mRNA expression is associated with tumor grade and histological type in gliomas and may be used as an independent prognostic factor, particularly for survival in LGG patients." (PMID 34638718, 2021). "Similarly, glioblastoma patients have remarkably higher expression of ADAM9 compared to patients with lower-grade gliomas, suggesting that ADAM9 is associated with the glioma severity." (PMID 33260155, 2020). "Further analysis of the association between ADAM9 expression and tumor grade of glioma patients revealed a significant association between ADAM9 expression and glioma malignant grade (p = 0.001), which indicates that ADAM9 is correlated with the severity of glioma." (PMID 33260155, 2020). "Additionally, we also found that the ADAM9 expression level was significantly associated with 1p/19q co-deletion in patients with lower-grade gliomas (p = 0.002, Chi-square test)." (PMID 27571068, 2016). "ADAM8 and ADAM19 are correlated with the invasive activity of glioma cells and may be associated with unfavorable survival, while ADAM9 is associated with tumor grade and histological type in gliomas and might be an independent prognostic factor, especially in LGG patients." (PMID 34638718, 2021). "Moreover, ADAM9 expression was significantly associated with glioma malignant grade." (PMID 33260155, 2020). "USP39 promotes ADAM9 pre-mRNA maturation, which alters integrin β1 expression and activity and promotes migration and invasion of human glioma cells." (PMID 40990019, 2025). "Our cophenetic correlation coefficient calculations (CCC) are in support of EMMPRIN/CD147, CD99, Cathepsin D, Intβ1, ADAM9/-17, and Galectin-3 being suitable biomarkers for glioma cells and potentially, SLGCs." (PMID 38306361, 2024). "Meanwhile, to further confirm the rescue effect of ADAM9 on the USP39‐regulated migration and invasion of glioma cells, we knock down the expression of ADAM9 in USP39‐overexpressed U87 cells." (PMID 33811456, 2022). "ADAM9 was found to be highly expressed in glioma samples and promoted migration and invasion in glioma cells." (PMID 35071748, 2022).
glioma (continued). "Although the abnormal expression of ADAM9 mRNA and protein has been investigated in glioma, the mechanisms controlling the processing of ADAM9 mRNA are still little known." (PMID 33811456, 2022). "used a three-dimensional matrix and revealed that some proteinases are associated with TNC-mediated invasiveness, such as MMP-12 in U178 and U251 glioma cell lines, as well as ADAM-9 in glioma patient-derived GSC lines." (PMID 36033448, 2022). "One study reported that miR-140 acted in glioma cells by adversely modulating a newly discovered target, called ADAM9." (PMID 35071748, 2022). "Among them, ADAM9, ADAM12, ADAMTS7, ADAMTS9, and ADAMDEC1 were the proteases where increased expression associated with poorer prognosis of glioma patients." (PMID 36172139, 2022). "TMA of 63 human gliomas were analyzed to further confirm the expression correlation of USP39/ADAM9 axis." (PMID 33811456, 2022). "Thirdly, we found that ADAM9 protein and miR-1272 levels exhibited inverse expression patterns in clinical glioma samples." (PMID 33260155, 2020). "In summary, we found that a novel tumor-related microRNA, miR-1272, is exceedingly downregulated in glioma tissues, and we identified a link between miR-1272 and ADAM9." (PMID 33260155, 2020). "Due to our limited number of samples, ADAM9 expression data in glioma were obtained from the TCGA database." (PMID 33260155, 2020). "The expression of ADAM9 was markedly decreased or increased after overexpression or inhibition, respectively, of miR-1272 in glioma cells." (PMID 33260155, 2020). "Taken together, these data lead us to believe that reduced miR-1272 expression and increased ADAM9 protein expression are frequent events in human glioma tissues." (PMID 33260155, 2020). "Secondly, ADAM9 expression was found to be significantly decreased in glioma cells overexpressing miR-1272." (PMID 33260155, 2020). "Based on the RNA-seq data from 303 glioma patients, the elevated mRNA expression of ADAM9 is correlated with poor progression-free survival and overall survival." (PMID 33096780, 2020). "ADAM9 inhibition had already been shown to reduce migration and invasion of human glioma cell lines." (PMID 33176868, 2020). "The negative regulation of ADAM9 by miR-1272 contributes to the functional effects of miR-1272 in the progression of glioma." (PMID 33260155, 2020). "Among these, 14 genes showed a statistically significant difference in the mRNA expression between different grades of gliomas, including ADAM9." (PMID 27571068, 2016). "Further studies would be required to elucidate the precise function of ADAM9 protein in gliomas, in addition to understanding the contribution/role of other ADAM family members." (PMID 27571068, 2016). "Our study analyzed for the first time the expression of ADAM9 in a large number of human glioma patients." (PMID 27571068, 2016). "Surprisingly, ADAM9 has rarely been investigated in gliomas, and to our knowledge, very little information is available so far on its role in gliomas." (PMID 27571068, 2016). "The ADAM9 gene was identified to be a new direct target gene of miR-140 in glioma patients." (PMID 35071748, 2022). "Altogether, our data show that USP39 induces mRNA maturation and elevates the expression of ADAM9 in glioma cells and may thus be considered potential target for treating patients with glioma." (PMID 33811456, 2022). "miR-140 could inhibit expression of ADAM9 and thereby suppress proliferation, invasion, and migration of glioma cells." (PMID 35071748, 2022). "Collectively, USP39 expression positively correlates with ADAM9 expression in human glioma." (PMID 33811456, 2022). "Meanwhile, over-expression of ADAM9 abrogated the inhibitory effect of miR-140 in glioma cells." (PMID 35071748, 2022).
glioma (continued). "Results showed that USP39 promoted the migration and invasion of glioma cells by inducing the pre‐mRNA maturation of ADAM9, a metzincin cell‐surface protease involved in several biological processes such as cell migration and cell–cell interactions in several solid tumors." (PMID 33811456, 2022). "Therefore, to demonstrate further that ADAM9 acts as the target molecule of USP39 in the regulation of glioma cell migration and invasion, we examined the expression levels of integrin β1 in the shUSP39‐U251 cells in vitro and in vivo." (PMID 33811456, 2022). "In summary, USP39 promotes human glioma migration and invasion by inducing ADAM9 mRNA maturation." (PMID 33811456, 2022). "This study may provide a new molecular mechanism targeting ADAM9 in the migration and invasion of glioma." (PMID 33811456, 2022). "Western blot analyses showed higher ADAM9 expression in glioma tissues compared to normal tissues." (PMID 33260155, 2020). "Thus, inverse expression patterns of miR-1272 and ADAM9 in glioma tissues were observed, supporting our previous findings." (PMID 33260155, 2020). "Moreover, this study is the first to verify the role of the miR-1272/ADAM9 axis as a regulator of glioma proliferation, migration, and cell cycle progression." (PMID 33260155, 2020). "The miR-1272/ADAM9/CDCP1 pathway may serve as a potential candidate pathway for the prevention of glioma." (PMID 33260155, 2020). "Further study of the miR-1272/ADAM9/CDCP1 axis may provide us with a potential mechanism of glioma progression." (PMID 33260155, 2020). "Furthermore, CDCP1 served as a potential downstream molecule of miR-1272/ADAM9 signaling in glioma and promoted the proliferation and migration of glioma." (PMID 33260155, 2020). "Further, correlation analysis revealed a significant association between ADAM9 and CDCP1 in glioma." (PMID 33260155, 2020). "We also found that CDCP1 serves as a potential downstream molecule of miR-1272/ADAM9 in glioma." (PMID 33260155, 2020). "Moreover, overexpression of ADAM9 reversed the inhibitory effects of miR-1272 on glioma cell progression." (PMID 33260155, 2020). "In glioma specifically, ADAM9 expression is correlated with poorer clinical outcomes." (PMID 33260155, 2020). "However, ADAM9 was rarely investigated in gliomas, and thus far its precise function was still unclear." (PMID 27571068, 2016). "Therefore, in the current study, we have evaluated the ADAM9 mRNA expression in gliomas, using information from 303 glioma patients based on their RNA sequence data." (PMID 27571068, 2016). "In addition to ADAM9, several other members of the ADAM family have also been implicated in tumor growth and invasiveness of gliomas, such as ADAM10, ADAM12 and ADAM17." (PMID 27571068, 2016). "However, its role has rarely been investigated in gliomas and, thus, in the current study we have evaluated ADAM9 expression in gliomas and examined the relevance of its expression in the prognosis of glioma patients." (PMID 27571068, 2016). "Moreover, silencing of ADAM9 mimicked the activity of miR-140 as a tumor-suppressor gene in glioma." (PMID 35071748, 2022). "To detect precursor and mature ADAM9 mRNA, two primer pairs were specifically designed for a region of the longest ADAM9 transcript; we found that the ratio of spliced to unspliced ADAM9 mRNA was decreased or increased in the glioma cells with USP39 siRNA or overexpressed plasmid, respectively." (PMID 33811456, 2022). "Moreover, targeting the miR-1272/ADAM9/CDCP1 pathway may serve as a potential therapeutic strategy for glioma treatment." (PMID 33260155, 2020). "In the previous studies, miR-136-3p inhibits cell growth and metastasis by targeting solute carrier family 7 member 5 (SLC7A5) and ADAM metallopeptidase domain 9 (ADAM9) in thyroid cancer, suggesting that miR-136-3p might function as a tumor suppressor in cancers including gliomas." (PMID 32677950, 2020).
glioma (continued). "Thus, it would be important to understand whether these additional mechanisms do play any role in the contribution of ADAM9 to the progression of glioma and would require further investigation." (PMID 27571068, 2016). "LicoA was shown to exert anti-invasive properties against human glioma by targeting the MEK/ERK and ADAM9 pathways." (PMID 40002335, 2025). "Several studies reported that ADAM9, ADAM10, and ADAM17 showed high expression in glioma; meanwhile, ADAM9, as a potential regulator of glioma invasion, showed higher expression in GBM compared with LGG." (PMID 36172139, 2022). "Results derived from clinical samples and online databases confirmed correlations between the expression of ADAM9 and CDCP1 and both the severity and prognosis of glioma." (PMID 33260155, 2020). "Here, we detected the expression of ADAM9 and CDCP1 in glioma cells transfected with miR-1272 mimic or ADAM9 overexpression plasmid." (PMID 33260155, 2020). "Using qRT-PCR, we confirmed that the expression levels of FOXM1, PLAU, CYR61, THBS1 and ADAM9 are indeed significantly down-regulated upon HMGA2 depletion in TPC1115 GICs, U87MG glioma cells and SK-N-SH neuroblastoma cells." (PMID 27259253, 2016). "Furthermore, six fresh human glioma tissues were used to detect the expression levels of USP39 and ADAM9 by Western blotting." (PMID 33811456, 2022). "Gene expression profiling of glioma cells transduced with short hairpin RNA (shRNA) against USP39 revealed that disintegrin and metalloproteinase domain‐containing protein 9 (ADAM9), a molecule previously related to tumor cell migration and invasion, was significantly downregulated." (PMID 33811456, 2022). "Furthermore, the expression levels of several genes (PLOD3, SLC20A1, ADAM9, FBLIM1, SPOCD1, P4HB, PROS1 and SELENON) were positively correlated with glioma grades." (PMID 32091665, 2020). "Except for these studies, there are not very many studies directly linking ADAM9 with glioma progression." (PMID 27571068, 2016). "The similar mechanism of USP39 was also found in human glioma in which USP39 could induce ADAM9 mRNA maturation but not protein to promote glioma progression." (PMID 36582601, 2022). "However, it is not clear how the expression of ADAM9 is regulated in human glioma." (PMID 33811456, 2022).